FGF8 (fibroblast growth factor 8)
Diseases named in the same sentence as FGF8 in open-access papers (continued):
Sharing a sentence is not in itself a finding about the gene and the disease.
pancreatic ductal adenocarcinoma (1 paper, 2023). An infiltrating adenocarcinoma that arises from the epithelial cells of the pancreas. "Increased expression of FGF8 has also been reported in pancreatic ductal adenocarcinoma patients who have undergone neo-adjuvant therapy, suggesting that FGF8 is a prospective target for novel anticancer therapeutics." (PMID 37762545, 2023).
Papillorenal syndrome (1 paper, 2025). "Although there is no genetic evidence of FGF8 mutations in human Papillorenal syndrome, these findings suggest that ectopic expression of FGF8 in the Wolffian duct and its derivatives contributes to polycystic kidney disease." (PMID 40575596, 2025).
rectal tumor (1 paper, 2019). "In summary, the strong connection between FGF8/Survivin expression and therapy response in rectal tumor tissue underlines that they are predictive markers not restricted to mismatch repair-deficient tumors alone." (PMID 30276721, 2019).
renal dysplasia (1 paper, 2012). Renal dysplasia is a form of renal malformation in which the kidney(s) are present but their development is abnormal and incomplete. "In sharp contrast, Fgfrl1 null mice have a phenotype with renal dysplasia very similar to mice with a conditional disruption of Fgf8 or a compound disruption of the two receptors Fgfr1 and Fgfr2." (PMID 22432025, 2012).
rhabdomyosarcoma (1 paper, 2016). A rare aggressive malignant mesenchymal neoplasm arising from skeletal muscle. "Although, we currently do not known whether AZA directly changed the DNA methylation status of the Fgf8 promoter, our results follow previous studies indicating that hypomethylation in primary rhabdomyosarcoma tumors was correlated with higher Fgfr1 mRNA expression levels in." (PMID 27200347, 2016).
rheumatoid arthritis (1 paper, 2008). A chronic, systemic autoimmune disorder characterized by inflammation in the synovial membranes and articular surfaces. "An anti-FGF8 antibody is expected to attenuate the symptoms of rheumatoid arthritis." (PMID 18699993, 2008).
salivary gland tumors (1 paper, 2015). "Transgenic expression of FGF8 in mice can induce mammary and salivary gland tumors as well as development of ovarian stromal hyperplasia." (PMID 25473897, 2015).
seminoma (1 paper, 2013). A radiosensitive malignant germ cell tumor found in the testis (especially undescended), and extragonadal sites (anterior mediastinum and pineal gland). "Loss of Fgf8 and Fgfr1 expression in Xenopus reduces cilia length and expression of the human orthologs is reduced in seminoma specifically when compared to other GCTs." (PMID 23599692, 2013).
syndactyly (1 paper, 2019). A disease characterized by the presence of syndactyly, including syndromic and non-syndromic forms. "In Step II, acrocephalo-syndactyly syndromes caused by gain-of-function mutations of FGFR1/FGFR2 are associated with an increased activity of FGF8 and syndactyly." (PMID 31637260, 2019). "Since FIBULIN1 deficiency leads to increased FGF8 activity and syndactyly, these interactions may explain the pathogenesis of syndactyly in Shaker mice." (PMID 31637260, 2019). "In this model, Fgf8 expression is normal, indicating that retinoic acid acts downstream of Fgf8 in the pathogenesis of syndactyly." (PMID 31637260, 2019). "Selective inactivation of Smads 1 and 5 in mice results in overexpression of Fgf8 and syndactyly." (PMID 31637260, 2019). "However, since FGF8 is the key middle step mediating the pathogenesis of syndactyly, one may argue that syndactyly may be considered as a defect in the proximodistal axis (FGF8 is the main controller of this axis)." (PMID 31637260, 2019). "Suppression of Notch signaling leads to an increased expression of Fgf8 in the AER and syndactyly." (PMID 31637260, 2019).
syngnathia (1 paper, 2013). "Together our data demonstrates that Foxc1 – Fgf8 signaling regulates mammalian jaw patterning and provides a mechanistic basis for the pathogenesis of syngnathia." (PMID 24385915, 2013). "Therefore we hypothesized that diminished Fgf8 activity correlated with the pathogenesis of syngnathia." (PMID 24385915, 2013). "Thus Fgf8 may be required to maintain proper levels of Foxc1 in the PA1 mesenchyme and conversely Foxc1 may be required to maintain proper levels of Fgf8 in the PA1 oral ectoderm forming a feedback loop critical for jaw development and in the pathogenesis of syngnathia and TMJ agenesis." (PMID 24385915, 2013).
testicular cancer (1 paper, 2023). A primary or metastatic malignant neoplasm that affects the testis. "Expression of FGF8 also changes at the mRNA level in ovarian and testicular cancers of different histological types, and its expression correlates with the tumor stage, and mRNA copy number variations generally result in the abnormal expression of a protein." (PMID 37762545, 2023).
thanatophoric dysplasia (1 paper, 2015). A primary bone dysplasia with micromelia characterized by macrocephaly, narrow thorax, and distinctive facial features. "Combining gyrencephalic carnivore ferrets and genetic manipulations using in utero electroporation, here we successfully recapitulated the cortical phenotypes of thanatophoric dysplasia (TD) by expressing fibroblast growth factor 8 in the ferret cerebral cortex." (PMID 26482531, 2015).
tongue cancer (1 paper, 2017). A malignant neoplasm affecting the tongue. "Similar relationship between concurrent expression of LRP6/FGF8 and patient outcome was also observed in tongue cancer." (PMID 28880263, 2017).
tumor (31 papers, 2001 to 2025). "Recently, overexpression of FGF8 was found to be associated with tumor progression in the clinical samples of colorectal cancer patients." (PMID 37762545, 2023). "FGF8 expression was significantly associated with tumour grade and stage, and was a predictor of disease-specific survival in patients followed up for over 10 years." (PMID 15655558, 2005). "Univariable Cox proportional hazard regression revealed that high FGF8 expression, gender, tumor grading, tumor stage, lymph node stage, and adjuvant therapy significantly impacted patient OS." (PMID 39518064, 2024). "To further validate our findings, we performed FGF8 RNA in situ hybridization on sublevel tumor sections (n = 4)." (PMID 38897168, 2024). "According to this study, FGF8 expression increases from control to low- to high-grade EOC samples, demonstrating a positive connection between tumor grade and FGF8 expression." (PMID 37762545, 2023). "A total of 89% of the patients with low levels of FGF8 in their tumor tissue were responders, whereas in the group with high levels of FGF8, only 44% responded well to the nCRT (p = 0.003)." (PMID 35682714, 2022). "FGF8 immunoreactivity was more intense in tumor of elderly patients (one-way ANOVA; ≤40 n = 3, 40–60 n = 11, >60 n = 16; P = 0.046 7)." (PMID 33649301, 2021). "FGF8 signal was positively detected in both the cytoplasm and membrane in tumor cells, whereas only weak staining of FGF8 was observed in majority of normal tissues (t-test; OSCC n = 30, normal n = 28; P < 0.000 1)." (PMID 33649301, 2021). "This allowed the identification of the zinc-finger transcription factor SP8 as a major factor involved in metastatic traits in malignant childhood liver tumors and revealed FGF8 as the main mediator of the SP8-induced aggressive tumor phenotype." (PMID 32824198, 2020). "FGF8 is also involved in later stages of tumor progression by increasing tumor cell invasion and migration as well as angiogenesis and bone metastasis." (PMID 28852180, 2017). "We next analyzed the relationship between FGF8 expression in tumor tissues and the clinic-pathological parameters of the 97 CRC patients." (PMID 25473897, 2015). "The staining intensity for FGF8 in tumor cells was significantly higher than in normal mucosal epithelial cells." (PMID 25473897, 2015). "In cell culture and transgenic animal models, FGF8 facilitates breast, prostate and ovarian cancer tumorgenesis, and increases tumor growth and angiogenesis by autocrine and paracrine loops." (PMID 25473897, 2015). "FGF8 expression was found to be overexpressed in CRC tissues compared with adjacent non-tumor tissues at both the mRNA and protein levels." (PMID 25473897, 2015). "As expected, the transplantation of undifferentiated hESCs at day 14 (before SHH and FGF8 induction) showed tumor formation." (PMID 24171168, 2013). "Retroviral insertions were present in the mouse homologs of 10 genes tagged in the zebrafish tumor samples: Brd2, Cirbp, Fgf8, Hexim1, Map2k5, Mmp14, Ncoa2, Slc30a5, Sox4, and Sox5." (PMID 21533036, 2011). "Cases with tumours expressing both FGF-8 in the malignant epithelium and VEGF in the adjacent stroma had a significantly worse survival rate than those with tumours negative for both, or only expressing one of the two growth factors (P = 0.029)." (PMID 11506499, 2001). "Overexpression of FGF8 has been shown to increase tumor proliferation rate and angiogenesis." (PMID 37529254, 2022). "Using KRAB-mediated CRISPR-dCas9 interference directed against FGF8, we could show that FGF8 is essential for the SP8-mediated aggressive tumor behavior." (PMID 32824198, 2020). "We may conclude that increased expression of FGF8 might play a role in tumor initiation and progression by inducing the odontogenic epithelium in cases of SMA." (PMID 30079292, 2018). "Consistent with this, FGF8 can also promote tumor growth and metastasis in mouse models." (PMID 25473897, 2015).
tumor (continued). "A significant association was observed between tumour VEGF and FGF-8 expression (P = 0.004)." (PMID 11506499, 2001). "Therefore, a TCGA analysis and immunohistochemistry, including tumor tissue from patients before and after neoadjuvant treatment, was performed to investigate the prognostic role of expression of FGF8, FGF18, and FGFR4 in adenocarcinomas of the esophago-gastric junction." (PMID 31527546, 2019). "Since FGF family members display oncogenic actions that can drive autocrine proliferation in cancers of the breast and ovary, the functional effects of FGF8 on Ten-2 expression in these tumors could be relevant for tumorigenesis and tumor growth, and therefore warrants further investigation." (PMID 28472127, 2017). "Investigating these classical markers in our data, we did observe a statistically significant increase of TNF (TNF‐α) in G1 tumors, FGF14 in G2 tumors, and FGF8, FGF18, and PDGFA in G3 tumor in comparison to pancreatic islet cells." (PMID 39245631, 2025). "Conclusively, a comparison of FGF8 expression in low- and high-grade EOC and control samples adds to the evidence that FGF8 expression correlates with tumor grade." (PMID 37762545, 2023). "Correlation of clinicopathological parameters and expression of FGF8, FGF18, and FGFR4 in the tumor tissue revealed significant correlations of the FGF8 protein level with tumor size ((y)pT), UICC stage, and Mandard regression grade." (PMID 31527546, 2019). "In a study of FGF-8 expression in OC, this cytokine was localized to tumor cells, whereas its receptors FGFR1, FGFR2, and FGFR4 were expressed by tumor cells, and to lesser extent, in stromal cells." (PMID 24860785, 2014). "FGF8 was identified as an oncogene on the basis of overexpression of FGF8 in NIH3T3 cells leading to focus formation, growth in soft agar and tumour formation in nude mice." (PMID 11953856, 2002). "Furthermore, this is the first study comparing the expression of FGF8, FGF18, and FGFR4 in tumor tissue available before and after neoadjuvant treatment." (PMID 31527546, 2019). "Besides FGF8, FGF18, and FGFR4 the factors age, gender, tumor differentiation, UICC stage, lymph node ratio, adjuvant treatment, and Mandard regression grade (in neoadjuvantly treated patients only) were included." (PMID 31527546, 2019). "Taken together, these results demonstrate that FGF8 contributes to the proliferative and metastatic capacity of CRC cells and may represent a novel candidate for intervention in tumor growth and metastasis formation." (PMID 25473897, 2015). "Furthermore, during early embryonic development, FGF8 has been shown to mediate EMT, which has been noted as a critical event in the late stages of tumor progression." (PMID 25473897, 2015). "Interestingly, ligands for this receptor, FGF2, FGF17, FGF8, and FGF19, were also overexpressed in the tumour." (PMID 26998479, 2015). "The administration of FGF8, FGF17, or FGF18 could resist apoptosis and enhance the survival of serum-starved tumor cells, including HCC-1.2, HepG2, and Hep3B cells, the mechanism studies have found that these effects were mediated by ERK and AKT/mTOR signaling pathways." (PMID 33935756, 2021). "We could show that SP8 and FGF8 expression was increased only in the primary tumor, but not in the metastasis, as compared to adjacent normal liver." (PMID 32824198, 2020). "Strong FGF8 staining was mainly observed in the cytoplasm of tumor cells, while weak FGF8 expression was detected in the proliferative zone of colorectal epithelium in normal colorectal tissue, but no FGF8 expression was detected in superficial colorectal epithelial cells." (PMID 25473897, 2015).
cancer (27 papers, 2002 to 2025). A tumor composed of atypical neoplastic, often pleomorphic cells that invade other tissues. "By analyzing tissue samples from 122 patients, who underwent surgical removal of their cancer, the study discovered that an increase in FGF8 protein levels is associated with a reduced chance of survival." (PMID 39518064, 2024). "While prior studies have linked aberrant expression of fibroblast growth factor 8 (FGF8) to various cancer types, its precise role has remained elusive." (PMID 39309198, 2024). "The regulation of growth and progression of hormonal cancer is regulated by FGF8, and any modification in the growth factor signaling cascade is linked to cancer progression." (PMID 39309198, 2024). "FGF8 expression is closely associated with the degree of degeneration in different cancer patients." (PMID 36629518, 2023). "Around 50% of clinically localized human PC express increased FGF8, while 80% or more of advanced cancers express increased FGF8." (PMID 38622735, 2024). "In various cancers, including adenocarcinomas of the gastroesophageal junction, the prognostic value of FGF8, a member of the FGF subfamily 8, has already been examined." (PMID 39518064, 2024). "While the FGF8 pathway is indeed well documented in other cancers, its role in therapeutic resistance, particularly in ESCC, remains largely unexplored." (PMID 39518064, 2024). "A significantly higher expression of FGF8 mRNA was observed in advanced-stage EOC than in early-stage EOC, which endorses its association with cancer progression." (PMID 37762545, 2023). "FGF8 gene silencing in SKOV3 cells adversely affected various cell properties essential for cancer cell survival and metastasis." (PMID 37762545, 2023). "This was unexpected given the oncogenic properties typically attributed to FGF8 and the cancer suppressive activities seen with Rlip knockdown." (PMID 35158795, 2022). "It has been demonstrated that FGF8 is involved in regulating migration and invasion in cancer cells." (PMID 33649301, 2021). "IPA analysis of these unique up-regulated genes indicated that some genes were associated with cell transformation during cancer progression (ABL1, TRIO, FOSB, NRCAM, TRIB2 and CDK6) and others with cell survival (e.g., BCL10, BBC3, FGF8, HSPA4 and SOD1)." (PMID 29137349, 2017). "We analyzed the methylation status of these genes in TCGA database and found the methylation of SHE, HSPA6 and FGF8 were lower in normal tissue then cancer tissue." (PMID 29029430, 2017). "It is clear that a more favourable environment for FGF8, and in particular FGF8b appears to be acquired in cancer progression." (PMID 12778074, 2003). "This was tested by means of fluorescent in situ hybridisation in 20 cancer specimens to map the FGF8 gene locus." (PMID 12778074, 2003). "In addition, several types of cancer cells acquire an aggressively altered phenotype due to the overexpression of FGF8." (PMID 39309198, 2024). "Also, silencing of the FGF8 gene in SKOV3 cells caused detrimental effects on several cellular properties crucial for cancer cell survival and metastasis, implying a potential prometastatic role of FGF8 in EOC." (PMID 39309198, 2024). "Encoding a transmembrane protein named amnionless, AMN is involved in the plasma membrane transport of Cubilin, and may influence cancer progression through the Cubilin-FGF8 (fibroblast growth factor 8) interaction." (PMID 37143087, 2023). "However, aberrantly increased FGF8 expression is involved in the development of several forms of hormone dependent cancers, and engineered overexpression of FGF8 is found to promote cancer cell invasion in animal models." (PMID 33649301, 2021). "Based on the microarray data, our results confirmed that relative expression of FKBP4, c-myc and FGF8 were significantly higher in both low (Gleason score = 6) and high grades (Gleason score > 6) of cancer as compared to that of the mean BPH samples in a larger cohort." (PMID 28852180, 2017).
cancer (continued). "FGF8 is also known to confer an aggressive transformed phenotype to several cancer cells." (PMID 25473897, 2015). "To understand how FGF8 contributes to the development of EOC and to shed light on plausible molecular mechanisms, we knocked down FGF8 and studied various properties of cancer cells." (PMID 37762545, 2023). "In summary, FGF8 and FGF18 are promising candidates for prognostic factors in adenocarcinomas of the esophago-gastric junction and new potential targets for new anti-cancer therapies." (PMID 31527546, 2019). "FGF8 has been commonly studied during developmental and pathological EMT, which is widely considered to contribute to cancer metastasis." (PMID 25473897, 2015). "FGF8 interacts with FGF receptors (FGFRs) to regulate fundamental developmental pathways during embryo development and also controls events such as cell proliferation, differentiation, cell survival, angiogenesis, and wound healing in cancer cells." (PMID 37762545, 2023). "It was proposed that co-treatment of MOLT-4 cells with TRAIL + kaempferol is a practical and striking approach to eliminate cancer resistance to TRAIL via intracellular anti-apoptotic protein inhibition, upregulation of DR4/5 and by suppression of the FGF-8 and VEGF-β expressions." (PMID 37239974, 2023). "However, the abnormal signaling of FGF8 subfamilies (FGF8, FGF17 and FGF18) have also been detected in many other cancers." (PMID 33802841, 2021). "FGF8, FGF18, and FGFR4 have been identified as promising biomarkers in a number of cancers; however no data exist on expression of FGF8, FGF18, and FGFR4 in adenocarcinomas of the esophago-gastric junction (AEG)." (PMID 31527546, 2019). "We have previously studied the expression of FGF8 mRNA in a series of malignant and non-malignant breast tissue and found that FGF8 transcripts are more frequently detected in malignant tumours and at a higher level than benign tissue." (PMID 11953856, 2002).
adenocarcinoma (2 papers, 2019 to 2020). A common cancer characterized by the presence of malignant glandular cells. "Until now, no data exists on the expression of FGF8, FGF18, and FGFR4 on adenocarcinomas of the esophago-gastric junction investigated by immunohistochemistry and no signifier scoring method is available." (PMID 31527546, 2019).
infection (2 papers, 2022 to 2026). The state of being infected such as from the introduction of a foreign agent such as serum, vaccine, antigenic substance or organism. "Here, using human A549 lung epithelial cells as the primary model, we identify fibroblast growth factor 8 (FGF8) as a crucial host factor whose expression is significantly elevated during infection by various IAV subtypes (including H1N1, H13N2, H9N2, and PR8)." (PMID 42171628, 2026).